HMGA2 (high mobility group AT-hook 2)
Diseases named in the same sentence as HMGA2 in open-access papers (continued):
Sharing a sentence is not in itself a finding about the gene and the disease.
adenoma (16 papers, 2014 to 2025). A neoplasm arising from the epithelium. "It has been reported that HMGA1 and HMGA2 nuclear expression levels are significantly higher in invasive adenomas than in non-invasive ones, particularly in GH-secreting adenomas, in which HMGA2 expression is higher than that in other PitNETs." (PMID 40362297, 2025). "For instance, RPSAP52, an antisense lncRNA from the HMGA2 locus, has been found to be overexpressed in both gonadotroph- and prolactin-producing adenomas of this gland, where its expression has been correlated with the expression of HMGA2." (PMID 34885097, 2021). "It has been reported that HMGA1 and HMGA2 nuclear expression levels are significantly higher in invasive adenomas than in non-invasive adenomas." (PMID 33574795, 2020). "Nascent epithelial tumors and early adenomas typically exhibit undetectable or low levels of HMGA2 mRNA and low to moderate levels of the HMGA2 protein product." (PMID 32365712, 2020). "Immunostaining in both adenomas and adenocarcinomas from Lin28bLo/Let7IEC-KO mice revealed frequent and intense co-staining of Hmga2 with nuclear β-catenin." (PMID 26244988, 2015). "Seven cases clearly overexpressed HMGA2 with expression levels ranging between 33.3 and 478.3, whereas in five FTCs the HMGA2 expression was within the range of adenomas (0.4 up to 5.73)." (PMID 24516594, 2014). "miR-23b and miR-130b, which were reduced in GH, gonadotroph, and NFPA adenomas, were demonstrated to target HMGA2 and cyclin A2, respectively." (PMID 25548562, 2014). "To gain insight into the association of several Let-7 targets with tumorigenesis in vivo, we examined Hmga1, Hmga2, Arid3a, and Hif3a protein expression by immunostaining adenomas and adenocarcinomas, as well as adjacent normal tissue, from Lin28bLo/Let7IEC-KO mice." (PMID 26244988, 2015). "Finally, an inverse correlation was found between miRNA expression and HMGA1 and HMGA2 protein levels in GH-secreting adenomas, suggesting a possible role of these miRNAs in the HMGA/E2F1 pathway, and thereby in the development of PAs." (PMID 26137461, 2015). "The expression of both HMGA1 and HMGA2 was significantly increased in aggressive adenomas or macroadenomas compared to in non-aggressive ones." (PMID 31487906, 2019). "Subsequently, it was shown that miR-23b and miR-130b, able to target HMGA2 and CCNA2, respectively, were drastically downregulated in GH, gonadotroph (FGA) and NFPA adenomas in comparison with normal pituitary gland and correlated with their respective targets." (PMID 31487906, 2019). "Moreover, the level of HMGA2 protein has been found positively correlated with tumor invasion and was significantly higher in grade IV than in grades I, II, and III adenomas." (PMID 26137461, 2015). "In a study including 110 patients with primary GC, 29 adenoma samples, and 30 non-cancerous gastric tissues, HMGA2 protein levels were found to be significantly high in GC samples, and the expression correlated significantly with lymphatic invasion, peripheral nerve invasion, and TNM stage." (PMID 36568211, 2022).
esophageal cancer (16 papers, 2012 to 2025). A primary or metastatic malignant neoplasm involving the esophagus. "Currently, research is mainly focused on non-coding RNAs as the molecular mechanisms related to HMGA2 during EMT in esophageal cancer." (PMID 38361784, 2024). "For example, Hsa_circ_0006948 affects mesenchymal transformation and promotes the development of esophageal cancer by regulating the miR-490-3p/HMGA2 signal axis." (PMID 35646112, 2022). "In esophageal cancer, the high expression of HMGA2 plays an essential role in regulating EMT." (PMID 38361784, 2024). "Furthermore, in vitro induced overexpression of miR-154 and Let-7 microRNAs in prostate and esophageal cancer cells abrogates HMGA2 expression and consequently EMT phenotype." (PMID 27027341, 2016). "Thus, Lin28 may increase proliferation of oesophageal cancer cells by directly inhibiting let-7 expression and subsequently upregulating HMGA2 and Myc, which are targets of let-7." (PMID 22433967, 2012). "Other studies have shown that the hsa_circ_0006948/miR-490-3p/HMGA2 signalling axis can regulate the EMT process in ESCC and promote the progression of oesophageal cancer." (PMID 37428781, 2023).
cervical carcinoma (14 papers, 2018 to 2024). A carcinoma arising from either the exocervical squamous epithelium or the endocervical glandular epithelium. "Here, we report that the phosphorylation level of HMGA2 was associated with the chemoresistance in cervical cancer cells." (PMID 34115920, 2021). "In the present study, we found that the phosphorylation level of HMGA2 was associated with the increased chemoresistance in cervical cancer cells." (PMID 34115920, 2021). "HMGA2 expression, with an AUC value of 0.910 (95% CI: 0.844–0.976), was a better potential diagnostic biomarker for distinguishing between cervical cancer and CINs than HPV copy number, which had an AUC value of 0.848 (95% CI: 0.772–0.923)." (PMID 29487700, 2018). "However, the underlying mechanisms of HMGA2‐mediated cisplatin resistance for cervical cancer remain largely unexplored." (PMID 34115920, 2021). "Our results reveal that CSNK2A1‐dependent HMGA2 phosphorylation may partially underlie cisplatin‐resistance in cervical cancer, suggesting that HMGA2 phosphorylation may have potential as a predicative biomarker and therapeutic target to improve chemotherapeutic efficacy." (PMID 34115920, 2021). "There were no significant changes in the expression of the miRNAs miR-608, miR-503-5p, and miR-337-3p or the mRNAs FXO6, TRAF4, and HMGA2, related to hepatoblastoma, cervical cancer, and endometrial cancer." (PMID 38474063, 2024). "To address this gap, we investigated the expression of HMGA2 in cervical cancer tissues and cell lines, and explored the role and potential mechanisms of HMGA2 in cisplatin resistance." (PMID 34115920, 2021). "Our findings support the potential role of HMGA2 as a novel target for cisplatin resistance and suggest the feasibility of combining cisplatin and HMGA2 inhibition for the improved chemotherapy of cervical cancer." (PMID 34115920, 2021). "Here, we report that HMGA2 is highly expressed in cervical cancer and negatively correlated with cisplatin‐induced cell death." (PMID 34115920, 2021). "In the present study, we found that HMGA2 was also involved in chemoresistance in cervical cancer, which was biologically consistent with our previous study." (PMID 34115920, 2021). "Cisplatin may enhance the interaction between HMGA2 and serine‐threonine kinase casein kinase II A1, thereby causing enhancement of HMGA2 phosphorylation in a time‐ and dose‐dependent manner, which in turn affects the bcl‐2/bax pathway and the resistance of cervical cancer cells to cisplatin." (PMID 34115920, 2021). "In the present study, we first reported the phosphorylation of HMGA2 played an important role in cisplatin resistance for cervical cancer, which prompts a new direction for investigating the effects of HMGA2 in the future." (PMID 34115920, 2021). "High expression of ER-α36 was correlated with a poor prognosis in cervical cancer by regulating HMGA2." (PMID 34336701, 2021). "The cutoff value determined using Youden's index and high sensitivity and specificity values indicate that HMGA2 levels increase dramatically when CIN progresses into cervical cancer." (PMID 29487700, 2018). "We then examined HMGA2 copy number variation in cervical cancer and CIN samples using fluorescence in situ hybridization (FISH)." (PMID 29487700, 2018). "In this study, integration of HPV into the HMGA2 gene was detected in only 2 samples, but HMGA2 protein expression was elevated in a much larger proportion of the cervical cancer samples." (PMID 29487700, 2018). "HMGA2 expression increased dramatically from CINIII to stage I cervical cancer, suggesting that HMGA2 is an important factor in the progression of CIN into cervical cancer." (PMID 29487700, 2018). "This indicates that HPV integration can at most account for only part of the observed overexpression of HMGA2 in cervical cancer." (PMID 29487700, 2018).
cervical carcinoma (continued). "HPV copy number and HMGA2 protein expression were evaluated as biomarkers for the transition of CIN into cervical cancer using receiver operating characteristic (ROC) curve analysis." (PMID 29487700, 2018). "Bcl-2 and Caspase 3 expression were examined to evaluate the potential role of HMGA2 in cervical carcinogenesis in SiHa, CaSki, and S12 cervical cancer cells." (PMID 29487700, 2018). "Transfection of HMGA2 siRNA decreased HMGA2 mRNA and protein expression, Bcl-2 expression, inhibited cell proliferation, and increased Caspase 3 expression and apoptosis in SiHa, CaSki and S12 cervical cancer cells." (PMID 29487700, 2018). "Furthermore, miR-302a-5p/367-3p and miR-142-3p act as tumor-suppressive miRNAs, playing a key role in the regulation of EMT by targeting HMGA2 in human cervical cancer." (PMID 38361784, 2024). "For the first time, the interaction of CSNK2A1 and HMGA2 was confirmed in cervical cancer." (PMID 34115920, 2021). "To evaluate whether HMGA2 has an impact on the chemoresistance of cervical cancer, we established stable HMGA2 knockdown cell lines with the specific plasmids and evaluated the HMGA2 expression by a western blot assay." (PMID 34115920, 2021). "The oncogenic protein high mobility group AT‐hook 2 (HMGA2) is involved in the development and progression of tumors, although its role in chemoresistance of cervical cancer remains unclear." (PMID 34115920, 2021). "Furthermore, HMGA2 protein levels were tested by immunohistochemical staining and found to be highly expressed in cervical cancer tissues compared to normal tissues." (PMID 34115920, 2021). "In sum, we have demonstrated that the CANK2A1/HMGA2/Bcl‐2/Bax axis modulates the sensitivity of cervical cancer cells to cisplatin, and potentially provides new therapeutic targets for overcoming chemoresistance in cervical cancer." (PMID 34115920, 2021). "Further research showed that HMGA2 was a downstream target of ER-α36 in cervical cancer cells." (PMID 34336701, 2021). "Furthermore, the functional gene at the downstream of ER-α36 was obtained via next-generation sequencing, and the biological functions of high mobility group A2 (HMGA2) in cervical cancer cells were investigated in vitro." (PMID 34336701, 2021). "In cervical cancer cells siRNA-induced HMGA2 downregulation inhibited cell proliferation and promoted apoptosis, showing a decreased BCL-2 expression and increased CASP 3 expression; on the contrary, HMGA2 overexpression caused opposite effects." (PMID 31963852, 2020). "Additionally, among EEC samples expressing HMGA2, protein levels were barely detected when compared with endometrium serous carcinoma or with endometrium benign lesions, such as glandular dysplasia and intraepithelial neoplasia." (PMID 31096664, 2019). "Because the proto-oncogene HMGA2 may play a crucial role in the transition of CIN into cervical cancer, treatments targeting HMGA2 might be potential therapeutic strategies." (PMID 29487700, 2018). "The HMGA2 levels in cervical cancer and CIN samples were also examined in an IHC assay." (PMID 29487700, 2018). "We also assessed the potential of HMGA2 as a biomarker for progression from CIN to cervical cancer." (PMID 29487700, 2018). "Both HPV copy number and HMGA2 protein expression were higher in cervical cancer than CIN samples." (PMID 29487700, 2018). "Notably, IHC staining also identified a significantly elevated level of HMGA2 in HPV-negative cervical cancer, suggesting that HMGA2 might be a potential biomarker in HPV-negative cervical cancer." (PMID 33997099, 2021). "Similarly, we speculate that in cervical cancer cells, estrogen promotes nuclear translocation of ER-α36, thereby directly regulating the transcription of HMGA2." (PMID 34336701, 2021). "This suggests HMGA2 may play a crucial role in the transition of CIN into cervical cancer." (PMID 29487700, 2018).
cervical carcinoma (continued). "The novelty of the present study is that we first demonstrated the role of the interaction of HMGA2 and CSNK2A1 in cisplatin resistance for cervical cancer." (PMID 34115920, 2021). "Variation in HMGA2 and HPV copy numbers among normal, CIN, and cervical cancer tissue samples were examined using FISH." (PMID 29487700, 2018). "We therefore investigated the utility of HMGA2 as a biomarker for cervical cancer by assessing genomic instability of the HMGA2 locus using FISH and HMGA2 protein expression using IHC." (PMID 29487700, 2018). "Furthermore, the present study confirmed the role of the interaction of HMGA2 and CSNK2A1 in cisplatin resistance for cervical cancer." (PMID 34115920, 2021). "In this study, the authors discovered the multiple genes in HPV-negative cervical cancer, including PRAME, HMGA2, ETV4, MEX3A, TM7SF2, SLC19A1, and TTYH3, which could contribute to HPV-negative cervical cancer development." (PMID 33997099, 2021). "We found that HPV copy number and HMGA2 protein expression both increased as CIN progressed into cervical cancer, but HMGA2 copy number did not." (PMID 29487700, 2018). "Thus, miR-142-3p directly targets HMGA1, HMGA2, HMGB1, and HMGB3, inhibiting them through reduction of cell viability, colony formation, migration, and invasion, as well as induction of apoptosis of tumor cells, particularly cervical cancer cells." (PMID 39062899, 2024). "However, the role of HMGA2 and CSNK2A1 in cervical cancer needs to be deciphered." (PMID 34115920, 2021). "Notably, the depletion of HMGA2 counteracted the epithelial-mesenchymal transition and lymph node metastasis by suppressing the attenuated total reflectance (ATR)/Chk1 signaling pathway in cervical cancer." (PMID 33997099, 2021).
endometrial cancer (14 papers, 2018 to 2025). Primary or metastatic malignant neoplasm involving the endometrium (mucous membrane that lines the endometrial cavity). "In summary, this study demonstrates that HMGA2 expression is associated with poor prognosis in endometrial cancer (EC), promoting disease progression potentially by inhibiting M1-polarized macrophage differentiation." (PMID 40703517, 2025). "These suggested that HMGA2 had good diagnostic and prognostic predictive value in endometrial cancer." (PMID 40703517, 2025). "The results indicated that HMGA2 expression was significantly upregulated in endometrial cancer, was significantly associated with poor clinical and pathological features of EC, and that patients with high HMGA2 expression had significantly decreased overall survival and disease-free survival rates." (PMID 40703517, 2025). "Moreover, based on the TCGA cohort, we analysed the association between the levels of HMGA2 and the clinicopathologic parameters of endometrial cancer patients." (PMID 29391048, 2018). "Utilizing the TIMER database, we investigated HMGA2’s role in modulating the endometrial cancer immune microenvironment." (PMID 40703517, 2025). "In this study, we utilized bioinformatics techniques and real clinical data to explore the differential expression and prognostic levels of HMGA2 in endometrial cancer." (PMID 40703517, 2025). "Comprehensive pan-cancer analysis of TCGA data revealed significant HMGA2 upregulation in multiple malignancies compared to matched normal tissues, including endometrial cancer." (PMID 40703517, 2025). "Complementary to pharmacogenomic predictions, HMGA2 depletion potentiated the cytotoxic effects of conventional chemotherapeutics in endometrial cancer models." (PMID 40703517, 2025). "HMGA2 exhibited significant upregulation in endometrial cancer (EC) tissues and correlated with poor patient prognosis." (PMID 40703517, 2025). "We obtained the methylation level of the HMGA2 promoter in endometrial cancer and normal tissues from UALCAN." (PMID 40703517, 2025). "Controversially, a recent study published by Ma and colleagues also reported the involvement of HMGA2 in endometrial cancer development and progression, demonstrating increased expression levels of HMGA2 in late stages, high-grade, and more invasive tumors." (PMID 31096664, 2019). "We observed that derepression of let-7 targets was the strongest GSEA signature obtained in DICER1 endometrial cancer, with known let-7 oncogene targets HMGA2 and IGFBP2 strongly deregulated." (PMID 31417090, 2019). "In the future, potential molecular therapies targeting the miRNA/HMGA2 axis should be explored as novel strategies to treat endometrial cancer." (PMID 29391048, 2018). "In the present study, high HMGA2 expression was correlated with poor clinical outcomes in endometrial cancer." (PMID 29391048, 2018). "In this study, the overexpression of miR-302a-5p/367-3p or knockdown of HMGA2 in endometrial cancer cells decreased the expression of EMT-related proteins, such as MMP-2, MMP-9, Snail, Slug and N-cadherin, while increasing the expression of E-cadherin." (PMID 29391048, 2018). "In endometrial cancer tissues, we showed that miR-302a-5p and miR-367-3p were significantly downregulated and thus inversely correlated with HMGA2." (PMID 29391048, 2018). "The immunohistochemistry results showed that the positive rate of HMGA2 protein expression in endometrial cancer was 80.0%, which was much higher than that of normal endometrial tissue (10.5%)." (PMID 29391048, 2018). "The disease-free survival curves for the endometrial carcinoma patients with high or low HMGA2 mRNA and protein expression indicated that high expression of HMGA2 correlates with poor clinical outcomes in endometrial cancer." (PMID 29391048, 2018).